MYEOV (myeloma overexpressed)
Diseases named in the same sentence as MYEOV in open-access papers (continued):
Sharing a sentence is not in itself a finding about the gene and the disease.
colorectal cancer (5 papers, 2019 to 2025). A primary or metastatic malignant neoplasm that affects the colon or rectum. "Taking a broader chromosome view shows that the two-pore segment channel 2 (TPCN2) gene had an H3K4me3 peak in the normal colon and colorectal cancer cell lines, whereas an H3K4me3 peak for the MYEOV gene was only observed in the colorectal cancer cell lines." (PMID 40141189, 2025). "MYEOV stimulated the migration of colorectal cancer cells and promoted the proliferation and invasion of colorectal cancer." (PMID 35395711, 2022). "The Myeloma Overexpressed (MYEOV) gene was identified as having a broad H3K4me3 domain in all colorectal cancer cells but not in normal colon samples." (PMID 40141189, 2025).
esophageal squamous cell carcinoma (5 papers, 2015 to 2025). Esophageal squamous cell carcinoma (ESCC) is a type of esophageal carcinoma (EC) that can affect any part of the esophagus, but is usually located in the upper or middle third. "A genomic analysis was performed on Japanese patients with stage I esophageal squamous cell carcinoma, and a marginal association was found between MYEOV genomic alterations and progression - free survival (P <.05)." (PMID 40535130, 2025).
lung cancer (5 papers, 2019 to 2025). A malignant neoplasm involving the lung. "In non–small-cell lung cancer, upregulation of the MYEOV transcript was associated with poor prognosis of the disease." (PMID 34169093, 2021). "Indeed, chr11q13.3 and MYEOV amplification status are also confirmed in the Cancer Cell Line Encyclopedia (CCLE)—lung cancer line dataset and the Tumorscape-NSCLC dataset." (PMID 30181549, 2019).
esophageal cancer (4 papers, 2021 to 2025). A primary or metastatic malignant neoplasm involving the esophagus. "A number of studies have already shown a strong association between MYEOV and multiple neoplasms including esophageal carcinoma 32, oral squamous cell carcinoma 33, neuroblastoma 34, colon cancer 35 and so forth." (PMID 34659542, 2021). "A previous study using esophageal cancer samples reported that the expression of MYEOV was inversely correlated with DNA methylation." (PMID 36698109, 2023). "Further research reported that after treating seven different esophageal cancer cell lines (KYSE-30, 170, 200, 510, 790, 960, and 1170) with 5-AzaCd, it was found that in one cell line (KYSE-170), the expression level of MYEOV was high, but there was no accompanying DNA amplification." (PMID 40535130, 2025).
pancreatic ductal adenocarcinoma (4 papers, 2021 to 2025). An infiltrating adenocarcinoma that arises from the epithelial cells of the pancreas. "Analysis of the TCGA PAAD cohort through the MethHC database revealed that the methylation level of the MYEOV gene promoter region in pancreatic ductal adenocarcinoma (PDAC) tissues is significantly lower than that in normal pancreatic tissues." (PMID 40535130, 2025). "has shown that high expression of MYEOV is significantly correlated with a low survival rate in patients with Pancreatic Ductal Adenocarcinoma (PDAC), with high expression of MYEOV promoting glycolysis in PDAC tumor cells." (PMID 40535130, 2025). "The MYEOV–MYC association may regulate microRNA levels to promote cell proliferation, as reported in pancreatic ductal adenocarcinoma." (PMID 41186354, 2025). "MYEOV was also identified as a gene amplified in several other malignancies, such as breast cancer, esophageal squamous cell carcinoma, pancreatic ductal adenocarcinoma, non-small cell lung cancer, and neuroblastoma, where it promotes cell proliferation and metastasis." (PMID 41186354, 2025). "Recent studies have reported that MYEOV could be a potential prognostic biomarker and therapeutic target of pancreatic ductal adenocarcinoma." (PMID 34134622, 2021). "In pancreatic ductal adenocarcinoma (PDAC), the knockdown of MYEOV reduces the expression levels of miR-17-5p and miR-93-5p." (PMID 40535130, 2025).
lung adenocarcinoma (3 papers, 2023 to 2025). A carcinoma that arises from the lung and is characterized by the presence of malignant glandular epithelial cells. "Studies have shown that myeloma over-expressed gene (MYEOV) is highly expressed in lung adenocarcinoma cells." (PMID 40959280, 2025). "As an oncogene that inhibits ferroptosis, MYEOV promotes the proliferation of lung adenocarcinoma (LUAD) and shortens patient survival, potentially making it a promising therapeutic target." (PMID 40535130, 2025). "Overexpression of MYEOV was also observed in bladder, colon, clear renal cell kidney, lung adenocarcinoma, rectum, and stomach cancers." (PMID 36698109, 2023). "Inhibition of MYEOV expression effectively promotes ferroptosis of lung adenocarcinoma cells." (PMID 40959280, 2025). "Conversely, MYEOV overexpression promotes the proliferation of lung adenocarcinoma cells." (PMID 40959280, 2025). "An inverse correlation between MYEOV and MXD4 expression levels was also observed in lung adenocarcinomas." (PMID 36698109, 2023).
gastric cancer (2 papers, 2023 to 2025). A primary or metastatic malignant neoplasm involving the stomach. "In gastric cancer, both CASTOR2 and MXD4 expression levels were inversely correlated with MYEOV expression levels." (PMID 36698109, 2023).
B-cell neoplasm (1 paper, 2019). A group of heterogeneous lymphoid tumors generally expressing one or more B-cell antigens or representing malignant transformations of B-lymphocytes. "MYEOV gene is localized at chromosome 11q13 that is a frequent site for chromosomal rearrangements in various carcinomas and B-cell neoplasms." (PMID 31828095, 2019).
bladder carcinoma (1 paper, 2019). "Moreover, the levels of MYEOV mRNA were significantly upregulated, and a positive correlation between MYEOV mRNA levels and MYEOV copy number, was observed in bladder carcinoma and gastric adenocarcinoma." (PMID 30181549, 2019).
glaucoma (1 paper, 2024). Increased pressure in the eyeball due to obstruction of the outflow of aqueous humor. "In this study, the SNPs with high OR values for cataract exposure on glaucoma were ZNF800 (rs62621812 with OR = 1.213), LOC338694;MYEOV (rs79721202 with OR = 1.144), BMP3 (rs72868578 with OR = 1.131), SOX2-OT (rs9823623 with OR = 1.093), and BET1L (rs11245997 with OR = 1.085)." (PMID 38674349, 2024).
liver fibrosis (1 paper, 2019). "Among the seven potential biomarkers FABP3, GALNT5, GPR84, ITGB6, MYEOV, PLEKHS1, and STRA6, we are particularly interested in GPR84 and STRA6 because they link to liver fibrosis that is a major risk factor in HCC and an independent risk factor of recurrence after hepatectomy." (PMID 31828095, 2019).
lymph node metastasis (1 paper, 2023). "Cox regression analysis using clinical information such as patient age, tumor size, lymph node metastasis, and sex showed that the expression of the MYEOV gene and lymph node metastasis were independent prognostic predictors." (PMID 36698109, 2023).
melanoma (1 paper, 2015). A malignant, usually aggressive tumor composed of atypical, neoplastic melanocytes. "Association between SNPs in the TPCN2/MYEOV region and melanoma." (PMID 25789475, 2015). "In summary, we provided confirmatory evidence of pleiotropic associations with melanoma for two SNPs in TERT-CLPTM1L and identified a potentially novel sex-specific association for a SNP near TPCN2/MYEOV." (PMID 25789475, 2015).
cancer (31 papers, 2010 to 2025). A tumor composed of atypical neoplastic, often pleomorphic cells that invade other tissues. "Kaplan-Meier survival analysis reveals a significant clinical phenomenon: high expression levels of the MYEOV protein are associated with shorter overall survival in cancer patients." (PMID 40535130, 2025). "MYEOV is identified as an oncogene that exhibits abnormal overexpression across various cancer types, particularly linked to the diminished survival rates of PAAD patients." (PMID 40141028, 2025). "We started with three tissues where MYEOV expression had previously been linked to cancer including lung, liver, and pancreatic tissue." (PMID 39139450, 2024). "Myeloma overexpressed gene (MYEOV) is a candidate proto-oncogene that is closely associated with gene recombination in many malignant tumors." (PMID 34930894, 2021). "While dysregulated expression of MYEOV transcript in cancer patients has been associated with its tumorigenic properties, the molecular mechanisms underlying MYEOV-mediated tumorigenesis are still largely unclear." (PMID 30181549, 2019). "This study focuses on MYEOV, an oncogene encoding for two protein isoforms, reported as causally involved in promoting cancer cell proliferation and metastasis in both haematological malignancies and solid tumours." (PMID 26568894, 2015). "Among orphan genes, MYEOV is considered a potential proto-oncogene, closely associated with gene rearrangement in various malignant tumors and correlated with poor prognosis in multiple types of cancer." (PMID 40535130, 2025). "In addition, at the 11q13.3 locus, we identify a conditional GWAS signal that is associated with MYEOV, a known cancer related gene." (PMID 41326661, 2025). "Overexpression of MYEOV has been associated with poor prognosis in different cancers." (PMID 39139450, 2024). "In cancer, it has been shown that the increased RNA expression of MYEOV can be caused by genomic rearrangements or duplications of 11q13 or by hypomethylation of MYEOV’s promoter." (PMID 39139450, 2024). "Again, the presence of the active chromatin state surrounding MYEOV was associated with tissues in which increased expression is commonly associated with the onset of cancer such as liver, pancreas, colonic mucosa, lung, breast epithelium and stomach smooth muscle." (PMID 39139450, 2024). "Another gene, MYEOV, is a region of cancer-associated genomic amplification." (PMID 36105089, 2022). "Although the dysregulated expression of MYEOV in cancer patients has been associated with its tumorigenic properties, the molecular mechanisms underlying MYEOV-mediated tumorigenesis, particularly in PDAC, remain largely unknown." (PMID 34930894, 2021). "In the discussion of the occurrence and progression of cancer, the role of the MYEOV protein cannot be overlooked." (PMID 40535130, 2025). "Elevated expression levels of MYEOV appear to be a potential predictive biomarker for anti-MYEOV therapy in several cancer types." (PMID 40535130, 2025). "The RNA expression levels of the MYEOV gene are closely related to the prognosis of cancer patients." (PMID 40535130, 2025). "After the expression of MYEOV increased in PDAC, analysis in multiple PDAC cell lines and normal HPDE cell lines showed that the expression levels of MYEOV in cancer cells increased." (PMID 40535130, 2025). "Given the significant role of MYEOV in multiple types of cancer, it has emerged as a promising biomarker, offering new perspectives for the diagnosis and prognosis of cancer." (PMID 40535130, 2025). "There is also debate over MYEOV protein function in cancer due to the presence of four upstream translation start sites, believed to render it impossible for MYEOV to be translated in human cells." (PMID 39139450, 2024).
cancer (continued). "We analysed PCHi-C data from primary tissues and cell lines in which we had not only shown an active enhancer chromatin state in MYEOV’s 3′ UTR and 3′ flanking region but also with documented MYEOV overexpression association with cancer." (PMID 39139450, 2024). "In other cancer samples in which MYEOV expression was elevated compared to normal tissue, the methylation levels of CpG3 were inversely correlated with mRNA expression." (PMID 36698109, 2023). "The report also notes that MYEOV has a very unusual feature as a cancer-related gene: the amino acid sequence significantly differs between humans and apes." (PMID 36698109, 2023). "Comparison of gene expression between normal pancreatic tissue in GTEx and TCGA-PAAD RNA-Seq data revealed that the MYEOV expression level is extremely low in normal tissues and is specifically upregulated in cancer tissues." (PMID 36698109, 2023). "Analysis of MYEOV expression levels and promoter methylation status in several cancers in the TCGA showed that the promoter region was hypermethylated in normal tissues, while some tumors showed hypomethylation and overexpression." (PMID 36698109, 2023). "We further compared the expression levels of MYEOV using TCGA data from other cancers and GTEx normal tissue datasets." (PMID 36698109, 2023). "Apart from SOX2, other genes involved in cancer aggressiveness, such as ZIC5, FAM83A, AADAC and MYEOV, were among the top most significantly associated genes and were associated with patient outcome." (PMID 36932385, 2023). "MYEOV is overexpressed in some cancers and contributes to tumorigenesis, metastasis and poor prognosis, including NSCLC." (PMID 35463335, 2022). "These in vitro results demonstrate that MYEOV likely plays a pro-cancer biological role in PDAC cells by promoting cell proliferation, migration and invasion." (PMID 34930894, 2021). "MYEOV is predominantly overexpressed and promotes tumorigenesis in various human cancers, including breast cancer, gastric cancer, colon cancer and non-small cell lung cancer (NSCLC)." (PMID 34930894, 2021). "In this study, by analyzing TCGA PDAC data and matched GTEx data, we found that MYEOV expression is associated with poor survival in PDAC patients and higher in carcinoma tissues than in healthy tissues." (PMID 34930894, 2021). "The genes CDC20, CDCA8, and CEP55 were prognostic in more than three (multiple) cancer types while other genes were specific for particular cancer types, such as MYEOV for PAAD." (PMID 32489468, 2020). "Within this group we observed the ETV4, ETV5 and MYEOV genes which have been shown to promote resistance to MAP Kinase inhibitors as well as promoting cancer cell proliferation, invasion and migration." (PMID 30717152, 2019). "The human cancer gene hst (fgf4) is situated approximately 9kb away from the MYEOV gene." (PMID 40535130, 2025). "Studies have shown that MYEOV may affect the expression of cancer-related genes through enhancer activity." (PMID 40535130, 2025). "For example, MYEOV expression is positively correlated with TMB in most cancers." (PMID 40478912, 2025). "Although the overexpression of MYEOV in cancer patients is associated with its oncogenic function, the underlying molecular mechanisms of the tumorigenic phenotype mediated by MYEOV have not been fully elucidated." (PMID 40535130, 2025). "Inhibiting the MYEOV gene may potentially reduce cancer cell metastasis and suppress the immune-suppressing ability of cancer cells." (PMID 40535130, 2025). "In order to further elucidate the possible function of the MYEOV locus in healthy and cancer cells, we have integrated publicly available epigenomics, 3D genome and comparative genomics data to characterise the MYEOV-3′-putative enhancer region and elucidate its evolutionary origins." (PMID 39139450, 2024). "The non-coding RNA transcript MYEOV has been shown to drive disease aggressiveness in cancer." (PMID 36932385, 2023).
cancer (continued). "It has been shown that MYEOV contributes to tumorigenesis in several types of malignant tumors." (PMID 35220962, 2022). "We cannot rule out the possibility that MYC may also regulate the target genes involved in the pro-cancer function of MYEOV." (PMID 34930894, 2021). "Taken together, these results suggest that amplification and overexpression of MYEOV gene may be an event frequently occurring in different types of cancers." (PMID 30181549, 2019). "MYEOV functioned as an oncogene and overexpressed in many cancers including LUAD." (PMID 29069717, 2017). "MET, AM25C, MROH9, MYEOV, FAM111B, Y6D, and PPP2R3A were highly expressed in the high-risk group, indicating that these genes may be related to the oncology process for patients with PAAD, and they seemed to be cancer-promoting genes." (PMID 35077391, 2022). "Furthermore, as we also observed that the expression of MYEOV is upregulated in other cancer types, MYEOV may also function as a ceRNA in these malignancies." (PMID 30181549, 2019). "Most of CEDGs like CCND1, ALDH3B1, MYEOV were frequently hypomethylated in cancer, while FGF3, FGF4, MRGPRF and CPT1A were hypermethylated in most cancers." (PMID 40478912, 2025). "mRNA expression of FAM83A, LY6D, MET, MUC16, MYEOV, and WNT7A were significantly elevated in cancer than healthy tissues (P<0.05)." (PMID 38169540, 2024). "In cancer, documented cases of DNA amplification at 11q13, primarily likely selecting for CCND1 proto-oncogene activation, often correspond to elevated MYEOV expression and an unfavourable prognosis." (PMID 39139450, 2024). "After observing increased MYEOV expression in PDAC, we analyzed MYEOV expression in 4 PDAC cell lines and 1 normal HPDE cell line and confirmed the increased MYEOV expression levels in cancer cells (P < 0.05)." (PMID 34930894, 2021). "Recent studies have shown that MYEOV, KCNN4, and S100A16 act as oncogenes and play vital roles in cancer progression." (PMID 34789165, 2021). "To assess the role of MYEOV in PDAC cell proliferation, we depleted MYEOV in two PDAC cancer cell lines (AsPC-1 and PANC-1) by transfecting cells with MYEOV-targeting siRNAs and then performing CCK-8 and colony formation assays." (PMID 34930894, 2021). "This highly conserved presumed enhancer element can regulate CCND1 in humans and mice, offering the possibility of studying the regulatory function of MYEOV in cancer using non-primate animal models." (PMID 40535130, 2025). "Analysis of multiple cancer samples revealed that the MYEOV promoter region is methylated in noncancer tissues but is demethylated in tumors, causing MYEOV overexpression in tumors." (PMID 36698109, 2023). "MYEOV has been found to have transcripts that do not match its protein expression levels in some cancers, as dramatically highly-expressed MYEOV transcripts cannot be translated to mature proteins in these cancer cells." (PMID 36358856, 2022). "Notably, the knockdown of MYEOV and DDX60L significantly inhibited the metastasis of cancer cells and induced apoptosis." (PMID 34789165, 2021). "This deeply conserved putative enhancer element could regulate CCND1 in both humans and mice, opening the possibility of studying MYEOV regulatory functions in cancer using non-primate animal models." (PMID 39139450, 2024). "Previously, MYEOV, KCNN4, S100A16, and FAM83A had been reported as oncogenes in various types of cancer, which could promote the proliferation and invasion of cancer cells." (PMID 34789165, 2021). "We did not identify any correlations of total gene expression with cancer status for the JAZF1, MSMB, HNF1B, MYEOV or CTBP2 genes." (PMID 20569440, 2010).